DEFA5 (defensin alpha 5)
Description:
Host-defense peptide that maintains sterility in the urogenital system. Has antimicrobial activity against a wide range of bacteria, including Gram-negative E.coli, P.aeruginosa and S.typhimurium, and Gram-positive E.aerogenes, S.aureus, B.cereus, E.faecium and L.monocytogenes. Confers resistance to intestinal infection by S.typhimurium. Exhibits antimicrobial activity against enteric commensal bacteria such as B.adolescentis, L.acidophilus, B.breve, L.fermentum, B.longum and S.thermophilus. Binds to bacterial membranes and causes membrane disintegration. Induces the secretion of the chemokine IL-8 by intestinal epithelial cells. Binds to B.antracis lef/lethal factor, a major virulence factor from B.anthracis, and neutralizes its enzymatic activity. (Microbial infection) Acts as a target for S.flexneri infection by binding to the bacterium, possibly via bacterial surface proteins, and thereby augmenting infectivity via enhanced bacterial adhesion and invasion of epithelial cells and tissues.
Synonyms: DEF5; HD-5
Tractability: Small molecule: it has a binding pocket of medium quality. Antibody: UniProt places it where antibodies can reach, with high confidence; its Gene Ontology location is reachable by antibodies, with high confidence; UniProt predicts a signal peptide or a membrane-spanning region.
Gene: Protein-coding gene on chromosome 8 (7,055,304 to 7,056,739, reverse strand). Ensembl gene ENSG00000164816.
Subcellular location: Secreted; Cytoplasmic vesicle, secretory vesicle
Subcellular location (Human Protein Atlas): Vesicles; Midbody; Predicted to be secreted
Pathways (Reactome):
Immune System: Alpha-defensins; Defensins
Cellular responses to stimuli: Mitochondrial unfolded protein response (UPRmt)
Gene Ontology:
Molecular function: protein binding; protein homodimerization activity; pore-forming activity
Biological process: antimicrobial humoral immune response mediated by antimicrobial peptide; defense response to Gram-negative bacterium; defense response to Gram-positive bacterium; innate immune response; killing of cells of another organism; positive regulation of interleukin-8 production; positive regulation of membrane permeability; protein homotetramerization; antibacterial humoral response; disruption of plasma membrane integrity in another organism; defense response
Cellular component: extracellular region; secretory granule; Golgi lumen; secretory granule lumen; transport vesicle
Genetic constraint (gnomAD): Loss-of-function variants: 10 observed, 7.75 expected, observed/expected ratio (o/e) 1.29, 90% interval 0.78 to 1.88. That is too few expected variants to judge how well the gene tolerates losing a copy. Missense variants: 131 observed, 85.55 expected, observed/expected ratio (o/e) 1.53, 90% interval 1.33 to 1.77. Synonymous variants: 37 observed, 31.64 expected, observed/expected ratio (o/e) 1.17, 90% interval 0.9 to 1.54.
Homologues: Orthologues: chimpanzee DEFA5 (95% identical), macaque DEFA4 (71% identical), rat Defa5 (50% identical), rabbit MCP-1 (47% identical), rat Defa31 (47% identical), rat Np4 (47% identical), rat RatNP-3b (43% identical), rat Np4 (41% identical), mouse Defa17 (36% identical), mouse Defa28 (36% identical), mouse Defa3 (36% identical), mouse Defa34 (36% identical), and 29 more. Paralogues in human: DEFA4 (50% identical), DEFA6 (49% identical), DEFA1 (48% identical), DEFA1B (48% identical), DEFA3 (48% identical).
Diseases named in the same sentence as DEFA5 in open-access papers:
DEFA5 is named in the same sentence as 38 diseases in open-access papers, as found by Europe PMC text mining. Sharing a sentence is not in itself a finding about the gene and the disease. The quoted sentences say what the papers report.
colitis (9 papers, 2018 to 2025). Inflammation of the colon. "DEFA5 expressed differentially in IBD and that aberrant expression, localization, and/or activation of DEFA5 underlies the tissue inflammation and damage associated with authentic CC form of colitis." (PMID 37854669, 2023). "EtOH feeding caused dramatic reduction of colitis-induced expression of Defa4, Defa5 and Defa6 genes." (PMID 30389960, 2018). "Interestingly, HD5 feeding caused a partial prevention of EtOH effect on colitis-induced expression of Defa4, Defa5 and Defa6 genes in colon." (PMID 30389960, 2018). "Given the importance of the inexact IC diagnosis, it is critical that these patients be studied in a larger cohort to fully address whether DEFA5 may be used as a diagnostic biosignature to differentiate IC into true CC or UC or other forms of colitis with different pathological characteristics." (PMID 41375691, 2025). "1A8 and 4F5 clones are worth studying in larger IBD cohorts to fully address whether DEFA5 expression may be used as a diagnostic biomarker to discrimination of the diagnosis of UC from CC or IC into authentic CC or UC or a colitis with different pathological characteristics." (PMID 39257990, 2024). "Defa5 was shown to alleviate mouse colitis via downregulating the expression of proinflammatory cytokines and inhibiting the NF-κB pathway." (PMID 33505592, 2021). "DEFA5 has shown the ability to delineate CC and UC phenotype and circumvents indeterminate Colitis (IC) into accurate authentic UC or CC." (PMID 37584007, 2020). "HD5 feeding partially blocked the effect of EtOH and DSS-colitis on Defa5 and Defa6 mRNA, but the effect on the mRNA for Defa4 gene was further reduced." (PMID 30389960, 2018). "Results of our present study show that DSS-induced colitis induces Defa4, Defa5 and Defa6 expression in mouse colon, and that EtOH feeding abrogates the colitis-induced expression of defensins in colon." (PMID 30389960, 2018). "The expression of Defa4, Defa5 and Defa6 genes was induced by colitis in the colon and EtOH feeding abolished this effect of colitis." (PMID 30389960, 2018). "Here, we characterize two mouse monoclonal antibodies, 1A8 and 4F5, specific to human DEFA5, an innate immune effector implicated in differentiating colonic inflammatory bowel disease (IBD) subtypes, particularly Ulcerative colitis, Crohn’s colitis and Indeterminate colitis." (PMID 41067337, 2025). "DSS-induced colitis significantly elevated mRNA for Defa4 and Defa5, but not Defa6 genes in the ileum." (PMID 30389960, 2018).
inflammatory bowel disease (8 papers, 2009 to 2025). A spectrum of small and large bowel inflammatory diseases of unknown etiology. "In Caco-2 cell lines, miR-924 is implicated in pathogenesis of inflammatory bowel disease by negatively regulating DEFA5 mRNA and protein expression." (PMID 32956382, 2020). "Interestingly, DEFA5 has been identified as a critical biomarker of inflammatory bowel disease and plays a crucial anti-inflammatory role." (PMID 36081904, 2022). "The role of undifferentiated cells, such as leucine-rich repeat-containing G protein-coupled receptor 5 (LGR5)-positive intestinal stem cells, in inflammatory bowel disease (IBD) development, is recognized, particularly within intestinal crypts where DEFA5-expressing Paneth cells are concentrated." (PMID 39329151, 2024). "The microbiota of mice expressing a human enteric α-defensin, DEFA5, has no segmented filamentous bacteria, which are responsible for inducing IL-17-producing Th17 cells, which have been correlated with inflammatory bowel disease (IBD) and colorectal cancer." (PMID 30158926, 2018).
gastric cancer (7 papers, 2011 to 2023). A primary or metastatic malignant neoplasm involving the stomach. "The underlying mechanisms of DEFA5 in the initiation and progression of gastric cancer await further studies." (PMID 37752551, 2023). "When overexpressing DEFA5 again in gastric cancer cell lines, this strongly diminished cell proliferation and the ability to form colonies." (PMID 36982340, 2023). "An ex vivo animal study shows the down-regulation of the DEFA5 gene in gastric cancer cells and that DEFA5 inhibits the growth of gastric cancer cells." (PMID 37752551, 2023). "The expression level of α-defensin 5 (DEFA5) was drastically downregulated in human gastric cancer." (PMID 36982340, 2023). "DEFA5 had inhibitory effect on the growth of gastric cancer cells and might play a potential antitumor role in gastric cancer." (PMID 36703795, 2022). "In an experiment of gastric cancer cells, DEFA5 overexpression dramatically increased the number of G1-phase cells but significantly decreased G2/M-phase cells, indicating that DEFA5 overexpression could result in cell cycle arrest at the G1 phase." (PMID 35296002, 2022). "The results on DEFA5 expression and its association with better OS give reason to assume that it may function as a tumor suppressor, which is in line with previous findings on the growth inhibitory effect of DEFA5 in gastric cancer." (PMID 35267585, 2022). "In gastric cancer, the overexpression of DEFA5 can inhibit cell proliferation and tumor growth." (PMID 34635074, 2021). "In 386 studies on DEFA5, two studies showed high expression in CRC and low expression in gastric cancer." (PMID 36703795, 2022). "Therefore, we believe that DEFA5 may play an anti-cancer role in the occurrence and development of CRC, consistent with previous results of gastric cancer." (PMID 36703795, 2022).
adenoma (5 papers, 2004 to 2023). A neoplasm arising from the epithelium. "In cancer-adenoma, we also found downregulation of DEFA5 and DEFA6, which encode α-defensins and are primarily expressed in Paneth cells of the small intestine." (PMID 31211760, 2019). "Of these, DEFA5 had been shown to be a key factor in the formation of adenomas, and has been proposed as a prognostic and predictive potential molecular biomarker in CRCs." (PMID 28455965, 2017). "RACK1, ACBP, CDH17 and EEF1G were significantly overexpressed in low-grade adenomas, whereas DEFA5 was significantly overexpressed in high-grade adenomas and suppressed in adenocarcinomas." (PMID 14710232, 2004).
ulcerative colitis (4 papers, 2012 to 2025). An inflammatory bowel disease involving the mucosal surface of the large intestine and rectum. "Bioinformatics analysis coupled with machine learning techniques suggested that DEFA5 is a pivotal gene that is significantly correlated with the progression of ulcerative colitis." (PMID 41050652, 2025). "The antimicrobial peptide DEFA5 has emerged as a promising biomarker for distinguishing IBD subtypes because its expression is restricted to colonic IBD conditions and associated with Paneth ileal-cell metaplasia, a feature more common in Crohn’s colitis than ulcerative colitis." (PMID 41067337, 2025). "The selected transcripts included the alpha defensins, (DEFA5 and DEFA6), which have exhibited altered regulation in ileal Crohn’s disease, and included cellular detoxification genes, which have exhibited altered regulation in ulcerative colitis." (PMID 22719822, 2012).
colon cancer (3 papers, 2020 to 2022). "DEFA5 was also found to be highly expressed in colon cancer tissues and showed strong killing effect on colon cancer cells without affecting normal host cells." (PMID 36703795, 2022). "Using the TCGA database, we found that the expression of DEFA5 in tumor tissues was generally lower than that in normal tissues, but the expression in colon cancer and rectal adenocarcinoma cells was significantly higher than that in normal tissues." (PMID 36703795, 2022). "DEFA5 is known for its high expression in secretory Paneth cells, which are found abundantly in the esophageal epithelium, but also in colon cancer, ovarian, endometrium, and pulmonary carcinomas." (PMID 35267585, 2022). "The expression of DEFA5 in tumor tissues was generally lower than that in normal tissues; however, the expression of DEFA5 in colon cancer and rectal adenocarcinoma cells was significantly higher than that in normal tissues." (PMID 36703795, 2022). "DEFA5 showed an inhibitory effect in colon cancer cell growth and may serve as a potential tumor suppressor in colon cancer." (PMID 36703795, 2022). "The protein expression of DEFA5 in colon tumors significantly increased." (PMID 36703795, 2022). "The defensin alpha 5 (DEFA5), an intestinal tissue-enriched protein, was specifically overexpressed in colon cancer." (PMID 33287876, 2020).
colorectal adenocarcinoma (2 papers, 2022 to 2024). The most common type of colorectal carcinoma. "Hence, DEFA5 was found to be closely related to colorectal adenocarcinoma." (PMID 36703795, 2022). "To further characterize the cells, we analyzed the 594 colorectal adenocarcinoma (COADREAD) patients listed in TCGA PanCancer Atlas26, and found that the expression levels of DEFA5 and 6 were correlated (R2 = 0.64)." (PMID 38182890, 2024).
colorectal cancer (2 papers, 2022 to 2023). A primary or metastatic malignant neoplasm that affects the colon or rectum. "Moreover, DEFA5 may be associated with better prognosis of colorectal cancer, while DEFA6 may be linked to a worse prognosis." (PMID 36982340, 2023). "More data is needed, but DEFA5 and DEFA6 seem to have a promising degree of specificity and sensitivity for predicting the prognosis of colorectal cancer." (PMID 36982340, 2023). "In contrast to this, DEFA5 and DEFA6 expression is significantly increased in colorectal cancer compared to healthy tissues." (PMID 36982340, 2023). "Further, we searched for 100 related genes of DEFA5 and DEFA6 in colorectal cancer, and speculated the possible role of them in the carcinogenesis of colorectal cancer by analyzing the role and pathway of the top genes." (PMID 36703795, 2022).
Obesity (2 papers, 2023 to 2024). Accumulation of substantial excess body fat. "Previous studies have shown that individuals with severe obesity display reduced defensin alpha 5 (Defa5) levels and that there is a negative correlation between serum lysozyme levels and body mass index." (PMID 39040602, 2024).
Sepsis (2 papers, 2022 to 2023). Sepsis is defined as life-threatening organ dysfunction caused by a dysregulated host response to infection. "In murine sepsis, increased ileal expression of TLR4 promoted the depletion of Paneth cells, and reduced lysozyme and defensin alpha 5 (DEF-5) expression exacerbated intestinal damage, and increased mortality rate." (PMID 38001795, 2023).
atopic dermatitis (1 paper, 2025). "IELs, intraepithelial lymphocytes; ADs, atopic dermatitis patients; DEFA5, defensin alpha 5.The abstract should ideally be structured according to the IMRaD format (Introduction, Results and Discussion)." (PMID 41050652, 2025).
autoimmune disease (1 paper, 2025). A disorder resulting from loss of function or tissue destruction of an organ or multiple organs, arising from humoral or cellular immune responses of the individual to their own tissue constituents. "In addition, a novel function of CD4+ IELs in the production of DEFA5 was discovered, indicating that CD4+ T lymphocytes may adopt new roles in the context of certain autoimmune diseases." (PMID 41050652, 2025).
Barrett esophagus (1 paper, 2023). Esophageal lesion lined with columnar metaplastic epithelium which is flat or villiform. "Another study indicates that DEFA5 produced from metaplastic Paneth cells may accelerate the initiation of Barrett’s esophagus, which is thought to be a precancerous lesion of esophageal adenocarcinoma." (PMID 37752551, 2023).
colonic adenomas (1 paper, 2021). "They demonstrated increased DEFA5 expression especially in colon adenomas indicating that it plays a role in tumorigenesis via the adenoma-carcinoma sequence." (PMID 35008210, 2021). "DEFA5 overexpression was shown in UC and CD patients compared to healthy controls as well as in patients with precancerous conditions such as colonic adenomas." (PMID 35008210, 2021).
diverticulitis (1 paper, 2024). An infection that develops in the diverticula of the intestinal tract. "Clones 1A8 and 4F5 recognized effectively the endogenous DEFA5 in active human diverticulitis (DV), UC, CC or IC disease samples, including transiently transfected HEK293T cells expressing DEFA5 with high degree of specificity and minimal non-confounding cross reactivity." (PMID 39257990, 2024).
esophageal squamous cell carcinoma (1 paper, 2021). Esophageal squamous cell carcinoma (ESCC) is a type of esophageal carcinoma (EC) that can affect any part of the esophagus, but is usually located in the upper or middle third. "Similarly, in esophageal squamous cell carcinoma, DEFA5 can inhibit the growth of cancer cells by down-regulating the expression of E-cadherin." (PMID 34635074, 2021).
gastric adenocarcinoma (1 paper, 2004). "Collectively, the upregulation of two CDX2-dependent genes, CDH17 and DEFA5, found in group 2, represents a characteristic of intestinal cellular lineage that is, in the stomach, implicated in the pathogenesis of intestinal-type gastric adenocarcinoma." (PMID 14710232, 2004).
gastric adenoma (1 paper, 2004). A neoplastic polyp that arises from the stomach. "On the one hand, the expression profiles of CDH17, DEFA5 and other CDX2 regulated genes may constitute specific tumour markers for a distinct subgroup of gastric adenomas with a progressive nature." (PMID 14710232, 2004).
gastritis (1 paper, 2022). Inflammation of the stomach. "DEFA5 upregulation inhibits the development of GC.Downregulation of defensins promotes the progression of Helicobacter pylori-associated gastritis." (PMID 36275647, 2022).
Hepatic steatosis (1 paper, 2016). Steatosis is a term used to denote lipid accumulation within hepatocytes. "Importantly, these results also demonstrated a therapeutic potential of DEFA5 for hepatic steatosis and MetS." (PMID 27895587, 2016).
Insulin resistance (1 paper, 2016). Increased resistance towards insulin, that is, diminished effectiveness of insulin in reducing blood glucose levels. "Indeed, insulin resistance was resolved, showing that the elevated fasting plasma glucose levels and the body mass by the HFD+VDD mice were improved through DEFA5 treatment." (PMID 27895587, 2016).
lung carcinoma (1 paper, 2021). "It was reported that DEFA5 peptide was highly presented in cancers, including lung cancer." (PMID 34635074, 2021).
necrotizing enterocolitis (1 paper, 2021). Necrotizing enterocolitis (NEC) is a devastating disease that affects mostly the intestine of premature infants. "In conclusion, this is the first study to show differences in DNA methylation of TLR4, VEGFA, and DEFA5 in infants affected by necrotizing enterocolitis." (PMID 33748044, 2021).
pyelonephritis (1 paper, 2012). An inflammatory process affecting the kidney. "With pyelonephritis (n = 6), mean DEFA5 expression increased to 7,829±1,052 transcripts per 10 ng RNA (p = 0.019)." (PMID 22359618, 2012). "With pyelonephritis, DEFA5 expression significantly increased in the kidney." (PMID 22359618, 2012). "Quantitative real-time PCR analysis performed on kidney tissues with pyelonephritis demonstrated a significant increase in DEFA5 expression compared to non-infected kidney tissues." (PMID 22359618, 2012).
salpingitis (1 paper, 2012). Acute or chronic inflammation of the fallopian tube. "This inducible pattern of expression is analogous to DEFA5 expression in the female reproductive tract where DEFA5 expression increases with salpingitis." (PMID 22359618, 2012).